MBLAC1 (metallo-beta-lactamase domain containing 1)
Description:
Endoribonuclease that catalyzes the hydrolysis of histone-coding pre-mRNA 3'-end. Involved in histone pre-mRNA processing during the S-phase of the cell cycle, which is required for entering/progressing through S-phase. Cleaves histone pre-mRNA at a major and a minor cleavage site after the 5'-ACCCA-3' and the 5'-ACCCACA-3' sequence, respectively, and located downstream of the stem-loop. May require the presence of the HDE element located at the histone pre-RNA 3'-end to avoid non-specific cleavage.
Synonyms: MGC49416
Tractability: PROTAC: its protein half-life has been measured.
Gene: Protein-coding gene on chromosome 7 (100,126,694 to 100,128,498, forward strand). Ensembl gene ENSG00000214309.
Subcellular location: Cytoplasm, cytosol; Nucleus
Gene Ontology:
Molecular function: metal ion binding; protein binding; RNA endonuclease activity
Biological process: histone mRNA metabolic process; mRNA 3'-end processing; positive regulation of G1/S transition of mitotic cell cycle
Cellular component: cytoplasm; nucleus; cytosol
Genetic constraint (gnomAD): Loss-of-function variants: 3 observed, 2.61 expected, observed/expected ratio (o/e) 1.15, 90% interval 0.48 to 1.89. That is too few expected variants to judge how well the gene tolerates losing a copy. Missense variants: 371 observed, 305.84 expected, observed/expected ratio (o/e) 1.21, 90% interval 1.11 to 1.32. Synonymous variants: 197 observed, 147.6 expected, observed/expected ratio (o/e) 1.33, 90% interval 1.19 to 1.5.
Homologues: Orthologues: chimpanzee MBLAC1 (99% identical), macaque MBLAC1 (95% identical), pig MBLAC1 (83% identical), guinea pig MBLAC1 (82% identical), dog MBLAC1 (82% identical), rat Mblac1 (71% identical), mouse Mblac1 (71% identical), tropical clawed frog mblac1 (46% identical), zebrafish mblac1 (42% identical), Drosophila melanogaster CG9117 (30% identical), Caenorhabditis elegans swip-10 (29% identical).
Diseases named in the same sentence as MBLAC1 in open-access papers:
MBLAC1 is named in the same sentence as 5 diseases in open-access papers, as found by Europe PMC text mining. Sharing a sentence is not in itself a finding about the gene and the disease. The quoted sentences say what the papers report.
metabolic syndrome (1 paper, 2024). A cluster of metabolic risk factors for CARDIOVASCULAR DISEASES and TYPE 2 DIABETES MELLITUS. "Our findings of altered glucose and cholesterol homeostasis, along with changes in heart mass, suggest the presence of a metabolic syndrome that may drive the cardiovascular dysfunction associated with AD who demonstrate reduced MBLAC1 expression." (PMID 38410184, 2024).
Parkinson disease (1 paper, 2024). A progressive degenerative disorder of the central nervous system characterized by loss of dopamine producing neurons in the substantia nigra and the presence of Lewy bodies in the substantia nigra and locus coeruleus. "Based on previous research, pharmacological treatments that restore normal metabolic function via manipulation of Mblac1 pathways may be of benefit in the treatment of neurodegenerative disorders, including AD and Parkinson’s disease." (PMID 38410184, 2024).
cancer (1 paper, 2018). A tumor composed of atypical neoplastic, often pleomorphic cells that invade other tissues. "Depletion of MBLAC1 in cells significantly affects cell cycle progression thus identifying MBLAC1 as a new type of S-phase-specific cancer target." (PMID 30507380, 2018). "Our genetic and cellular studies imply that MBLAC1 inhibition may selectively slow down S-phase progression in cancer cells." (PMID 30507380, 2018). "Thus, the development of MBLAC1 inhibitors, likely for use in combination with other drugs, is of interest from the cancer treatment perspective." (PMID 30507380, 2018). "Thus, MBLAC1 may represent a new S-phase specific cancer target." (PMID 30507380, 2018).
cardiovascular disease (1 paper, 2024). "The form of AD linked to MBLAC1 expression has cardiovascular disease comorbidity." (PMID 38410184, 2024).
MBLAC1 also shares sentences with these, for which no sentence is quoted: neurodegenerative disease (1 paper).